POSTN (periostin)
Diseases named in the same sentence as POSTN in open-access papers (continued):
Sharing a sentence is not in itself a finding about the gene and the disease.
hepatocellular carcinoma (34 papers, 2014 to 2025). A malignant tumor that arises from hepatocytes. "In hepatocellular carcinoma, POSTN is associated with reduced survival as it promotes migration and invasion of tumor cells." (PMID 38275881, 2024). "Our findings here give further insights into the scavenging of fasciclin domain proteins TGFBi and POSTN, which are heavily implicated in liver fibrosis and hepatocellular carcinoma, through Stab1 and Stab2 and in liver fibrosis models." (PMID 37446152, 2023). "In HCC, POSTN-deficient mice showed reduced diethylnitrosamine-induced liver cancer, while POSTN expression in hepatocellular carcinoma was associated with a poor prognosis in human patients." (PMID 37446152, 2023). "Periostin is highly expressed in most solid tumors, such as stomach, pancreas, lung, breast, colon, and liver carcinomas." (PMID 40518514, 2025). "The Gut Microbial Metabolite TMAO has also been shown to promotes inflammatory hepatocellular carcinoma by upregulating POSTN." (PMID 38551775, 2024). "It is further found that POSTN induced residual hepatoma cells by SHS, acquiring stem cell characteristics through activating the integrin β-1/AKT/GSK3-β/β-catenin/TCF4/Nanog pathway." (PMID 36081558, 2022). "Subsequently, there was enhanced invasion of residual hepatoma cells through HSC-CM secreting POSTN." (PMID 36081558, 2022). "We also confirmed that POSTN was the most significantly altered differential gene in the inflammatory hepatocellular carcinoma environment." (PMID 35676936, 2022). "A study of resected hepatocellular carcinoma (HCC) specimens showed that high periostin levels were more frequent in cases of multiple tumors, presence of microvascular invasion, and advanced-stage disease." (PMID 32899501, 2020). "A strong POSTN expression has been observed in cancer epithelial cells and tumor stroma in hepatocellular carcinoma." (PMID 29946533, 2018). "Accumulating evidence indicates that the expression of periostin is positively correlated with tumor grade and stage in several types of tumor, including hepatocellular carcinoma, colorectal cancer and prostate cancer." (PMID 25369801, 2015). "Similarly, recent studies have shown that Periostin and TGFβ form a positive feedback loop in fibroblasts and in hepatocellular carcinoma." (PMID 39940700, 2025). "Both Stabilin ligands TGFBi and POSTN are part of the extracellular matrix in normal liver tissue and have previously been described as markers in various pathological processes in the liver, including hepatocellular carcinoma." (PMID 37446152, 2023). "Furthermore, the knockdown of POSTN was negatively correlated with the abilities of hepatocellular carcinoma cells to form tumours in mice." (PMID 35508298, 2022). "POSTN may therefore be an effective therapeutic target or prognostic marker for hepatocellular carcinoma." (PMID 35057799, 2022). "Study shows that periostin is associated with the progression of hepatocellular carcinoma and it could activate hepatic stellate cells through integrin–FAK–STAT3–periostin pathway." (PMID 35366885, 2022). "POSTN upregulated the stem cell characteristics in residual hepatoma cells by SHS." (PMID 36081558, 2022). "Increased tumor expression of periostin was also associated with advanced stages in colon, prostate, NSCLC and hepatocellular carcinoma (HCC) patients." (PMID 38279150, 2024). "In the hepatitis C virus (HCV)-related cohort, elevated levels of Periostin in the liver indicate an increased likelihood of adverse outcomes, such as hepatocellular carcinoma (HCC), in patients with liver fibrosis (GSE15654)." (PMID 38216590, 2024). "In patients with histologically-proven NAFLD (N. = 74; 10 with hepatocellular carcinoma, HCC) plasma periostin concentrations were analyzed." (PMID 33255560, 2020). "Previous study has found that three groups of cancer embryonic cells, including POSTN+ CAF, FOLR2+ TAM, and PLVAP+ EC, have close cellular communication connections in hepatocellular carcinoma." (PMID 39524442, 2024).
hepatocellular carcinoma (continued). "Similarly, in hepatocellular carcinoma (HCC), POSTN facilitates the generation and maintenance of CD133+ liver cancer stem cells." (PMID 40520021, 2025). "miR-876 targets POSTN and inhibits the epithelial mesenchymal transition (EMT) and fibrosis of hepatocellular carcinoma, thereby inhibiting the progression and prognosis of hepatocellular carcinoma." (PMID 35057799, 2022). "Serum POSTN levels have been shown to be increased in patients with hepatocellular carcinoma compared to healthy controls or patients with no cancerous liver diseases." (PMID 29946533, 2018).
colorectal cancer (31 papers, 2015 to 2026). A primary or metastatic malignant neoplasm that affects the colon or rectum. "High POSTN levels in tumors are associated with aggressive tumor behavior as well as advanced stage and/or poor prognosis in colorectal cancer." (PMID 33017516, 2020). "To further demonstrate the importance of high POSTN expression in the prognosis of colorectal cancer progression, we analyzed the correlations between POSTN expression and factors associated with the aggressiveness of colorectal cancer." (PMID 26023718, 2015). "Our results demonstrate that periostin is strongly expressed in cancer-associated fibroblasts (CAFs) and is closely associated with Smad2/3 expression, as well as malignant clinicopathological characteristics in colorectal cancer." (PMID 39941916, 2025). "Although periostin and Smad2/3 signaling have been independently linked to cancer progression, their expression patterns and correlations remain insufficiently understood in colorectal cancer (CRC)." (PMID 39941916, 2025). "Here we demonstrated that high POSTN expression was associated with serosal invasion, lymph node metastasis, tumor size and differentiation, which were crucial histological features associated with poor prognosis in colorectal cancer." (PMID 26023718, 2015). "This work aims to clarify the expression patterns of periostin and Smad2/3 signaling in colorectal cancer and their relationship with clinicopathological features." (PMID 39941916, 2025). "The present study revealed that patients with stromal periostin (POSTN)-positive colorectal cancer (CRC) with peritoneal and distant organ metastasis had a significantly worse 5-year survival rate." (PMID 36765564, 2023). "It has been also showed that periostin reduced apoptosis and increased chemoresistance in human colorectal cancer cells by upregulating the anti-apoptotic protein survivin and activating the PI3K/Akt/survivin pathway." (PMID 36224629, 2022). "Colorectal cancer is an example in which periostin significantly increases metastatic growth by promoting human endothelial cell survival and inducing angiogenesis." (PMID 36224629, 2022). "Aberrant POSTN expression has been found in multitude tumor entities, including head and neck, lung, neuroblastoma, breast, and colorectal cancers and HCC, for its roles in cell survival, EMT, angiogenesis, and tumor microenvironment construction." (PMID 33083453, 2020). "They observed that exogenous overexpression of periostin in colorectal cancer cell lines promotes liver metastasis growth in vivo, reduces stress-induced apoptosis, and enhances neo-vascularization." (PMID 32793478, 2020). "Taken together, these findings strongly support an important role for POSTN in the development, progression, and metastatic dissemination of colorectal cancer." (PMID 29946533, 2018). "Here we investigated the role of periostin (Postn), a matricellular protein that interacts with various integrin molecules on the cell surface, in colitis-induced colorectal cancer." (PMID 29731999, 2018). "In the present study, we performed immunohistochemical staining of POSTN protein and survival data analyses in colorectal cancer cells and their adjacent normal tissue counterparts in 115 cases." (PMID 26023718, 2015). "The positive expression rate of POSTN protein (59.13%, 68/115) in colorectal cancers was significantly higher than that in adjacent normal colon mucosa (0.47%, 11/109)." (PMID 26023718, 2015). "To investigate its prognostic value, we selected 115 cases of colorectal cancer and investigated the expression of POSTN by immunohistochemical staining." (PMID 26023718, 2015). "A low level of POSTN protein expression was detected in 93.13% (108/115) of colorectal cancer cells, which was significantly higher than in adjacent normal colon mucosa (31.30%, 36/115) cells." (PMID 26023718, 2015). "We examined POSTN protein in colorectal cancer specimens from 115 patients by strictly following up using immunohistochemistry." (PMID 26023718, 2015).
colorectal cancer (continued). "We found that the expression levels of the POSTN oncoprotein were significantly higher in colorectal cancers than in adjacent normal tissues." (PMID 26023718, 2015). "POSTN over-expression in colorectal cancers was positively correlated with tumor size, differentiation, lymph node metastasis, serosal invasion, clinical stage and five-year survival rates." (PMID 26023718, 2015). "Of particular interest, high POSTN expression was an independent hazard factor in colorectal cancer." (PMID 26023718, 2015). "Immunohistochemical staining revealed that the POSTN protein had a cytoplasmic expression pattern in colorectal cancer cells." (PMID 26023718, 2015). "To evaluate the relationship between POSTN protein expression and colorectal cancer progression, we further evaluated the correlation between POSTN expression and clinical-pathological characteristics." (PMID 26023718, 2015). "Further analysis showed that patients with advanced stage colorectal cancer and high POSTN expression levels had lower survival rates than those with early stage colorectal cancer and low POSTN expression levels." (PMID 26023718, 2015). "Similar results with an increased sample size would support POSTN as an independent prognostic marker for colorectal cancer." (PMID 26023718, 2015). "POSTN expression was commonly seen in cases with poor prognostic factors of colorectal cancer, leading to lymph node metastasis, advanced stage, serosal invasion and reduced survival time." (PMID 26023718, 2015). "In addition, a correlation was observed between higher preoperative serum POSTN levels in colorectal cancer patients and the formation of distant metastases or a poor prognosis in patients." (PMID 36077762, 2022). "In a colitis-associated colorectal cancer model using periostin-/- mice, lack of periostin expression resulted in fewer inflammatory peritoneal macrophages, as evidenced by a reduced expression of TNF-α and IL-1β, and up-regulation of TGF-β and IL-10." (PMID 33466303, 2021). "What is noteworthy is that, NCBI GEO gene expression database of TECs in colorectal cancer and lymphoma also verified the specific high expression of 7 out of these 12 ECM associated genes in TECs from colorectal cancer and lymphoma, i.e. SPON2, BMP-1, FN1, POSTN, THBS2, VCAN and AEBP1." (PMID 29541388, 2018). "In colorectal carcinoma, POSTN expression is increased compared with normal tissues." (PMID 29946533, 2018). "Finally, a multivariate analysis performed in patients with colorectal carcinoma showed that high expression of stromal POSTN was an independent prognostic biomarker of poor overall survival and progression-free survival." (PMID 29946533, 2018). "Cytoplasm immunohistochemical staining showed POSTN protein expression in colorectal cancers." (PMID 26023718, 2015). "For example, circulating periostin may help identify patients with more aggressive colorectal cancer." (PMID 26023718, 2015). "Importantly, we found that colorectal cancer with high POSTN expression was correlated with late-stage tumors." (PMID 26023718, 2015). "Our data showed that POSTN was frequently upregulated in colorectal cancers." (PMID 26023718, 2015). "Similarly, a high level of POSTN protein expression was detected in 59.13% (68/115) of colorectal cancers cells, which was significantly higher than that in adjacent normal colon mucosa (10.47%, 11/109) (p < 0.01)." (PMID 26023718, 2015). "Taken together, these results suggest that a high level of POSTN expression might be related to colorectal cancer progression." (PMID 26023718, 2015). "Thus far, there have been several reports on the role of periostin in colorectal cancer." (PMID 35056404, 2022). "Previous studies showed that overexpression of POSTN predicted a poor prognosis in non-small cell lung cancer and colorectal cancer and suggested that POSTN could be a regulator of inflammation in the tumor microenvironment and a potential therapeutic target in lung and colorectal cancers." (PMID 36550569, 2022).
colorectal cancer (continued). "Gene expression profiling of colorectal cancer samples revealed that high aneuploidy scores and microsatellite instability (MSI) correlate with increased expression of the POSTN gene (periostin), a factor known to remodel the extracellular matrix (ECM)." (PMID 38067140, 2023). "A significant positive correlation was shown between the increase in POSTN expression and metastases in various cancers, including NSCLC, breast, ovarian, pancreatic or colorectal cancer." (PMID 36077762, 2022). "In this study, we wanted to investigate the correlations between periostin, angiogenesis and the selected cytokines—TNFα, IFN-γ, IL-1β and IL-17—in the context of TUMOR–MARGIN interactions in colorectal cancer." (PMID 35056404, 2022). "Concerning the circulating periostin levels, there was strong evidence that serum level of periostin in NSCLC and colorectal cancer patients is significantly elevated." (PMID 27816968, 2017). "Periostin (POSTN) expression in cancer cells and circulation has been related to poor prognosis of colorectal carcinoma (CRC)." (PMID 26556874, 2016). "In this study, we analyzed tissue samples from 351 colorectal cancer patients and found that periostin is predominantly expressed in CAFs rather than cancer cells." (PMID 39941916, 2025). "Indeed, an increase of cell proliferation by periostin has been described at 100 ng/ml in cystic epithelial cells and 5 μg/ml in MIP101 colorectal cancer cells." (PMID 38039285, 2023). "However, the patterns of periostin and Smad2/3 expression and their relationship in colorectal cancer have not yet been reported." (PMID 39941916, 2025). "By contrast, a recent study comparing serum POSTN levels between patients with and without bone metastasis not found significant differences between both groups although, in this study, the number of patients with colorectal cancer was low." (PMID 29946533, 2018).
prostate carcinoma (31 papers, 2010 to 2025). A carcinoma that arises from epithelial cells of the prostate gland. "Higher microvessel density was found to be associated with high periostin expression in prostatic cancer." (PMID 35056404, 2022). "In prostate cancer, periostin increase Akt phosphorylation, which leads to the upregulation of Snail, which is a negative regulator of E-cadherin causing prostate cancer cells to invade more." (PMID 36224629, 2022). "High POSTN expression was associated with high fibronectin expression and low expression of integrin α4 in metastatic castration-resistant prostate cancer patients." (PMID 29946533, 2018). "High stromal expression of periostin was also observed to be associated with shorter survival of prostate cancer." (PMID 25781169, 2015). "In most of these tumour entities, periostin has been associated with more aggressive tumour characteristics, which is perfectly in line with our findings in prostate cancer." (PMID 20534149, 2010). "Inhibition of periostin in prostate cancer cells caused an inhibition of cellular proliferation." (PMID 38398019, 2024). "Among them, several proteins such as serpin B3, renin receptor, and periostin have been reported as pathological markers for renal failure and prostate cancer, respectively." (PMID 33928097, 2021). "Exploring the biological function of periostin (POSTN) in prostate cancer (PCa) bone metastasis is of importance." (PMID 35087756, 2021). "Particularly, POSTN upregulated E-cadherin expression and suppressed cell invasiveness in bladder cancer cells while the opposite effects were observed in prostate cancer cells, suggesting that POSTN effects regarding EMT are tumor cell-dependent." (PMID 29946533, 2018). "Periostin upregulated snail expression in prostate cancer cells but downregulated Twist expression in bladder cancer cells." (PMID 27034956, 2016). "In prostate cancer, IHC analysis showed POSTN expression was up-regulated in high-grade prostate cancers and stromal POSTN was shown to be a progression factor for prostate specific antigen relapse-free survival." (PMID 26716408, 2016). "The results show that the periostin staining is positively correlated with the aggressiveness of prostate cancer." (PMID 25781169, 2015). "Previously, we identified periostin to be up-regulated in aggressive prostate cancer (CaP) using quantitative glycoproteomics and mass spectrometry." (PMID 25781169, 2015). "Increase in COMP and periostin expression and decrease in VAP-1 expression in prostate have been shown to be associated with aggressive prostate cancer." (PMID 26023718, 2015). "Recent studies have revealed that periostin is involved in the development of various tumors, such as breast, colon, lung, ovarian cancer, and prostate cancer." (PMID 25781169, 2015). "This is the first study using such an expanded cohort to analyze periostin expression in prostate cancer and try to determine the clinical relevance of periostin elevation with the CaP aggressive phenotype." (PMID 25781169, 2015). "Periostin (POSTN) expression in prostate cancer (PCa) and in normal specimens was evaluated in 90 patients by an immuno-reactive score(IRS) based on the intensity of immunostaining and on the quantity of stained cells." (PMID 23273263, 2012). "In our recent study, Periostin was up-regulated in prostate cancer(PCa) compared with benign prostate hyperplasia (BPH) by proteomics analysis of prostate biopsies." (PMID 21714934, 2011). "The correlation between periostin expression and poor prostate cancer patient outcome is consistent with previous studies that identified periostin overexpression in several invasive tumor types." (PMID 21611158, 2011). "Further functional studies are needed to shed light on the mechanism of periostin up-regulation in prostate cancer." (PMID 20534149, 2010).